INHCAP (inhibitor of carbonic anhydrase pseudogene)
Synonyms: formerly TFP; TFP1
Gene: Transcribed unprocessed pseudogene on chromosome 3 (133,688,192 to 133,712,802, forward strand). Ensembl gene ENSG00000242337.
Diseases named in the same sentence as INHCAP in open-access papers:
INHCAP is named in the same sentence as 1 disease in open-access papers, as found by Europe PMC text mining. Sharing a sentence is not in itself a finding about the gene and the disease.
INHCAP shares sentences with these, for which no sentence is quoted: infectious disease (1 paper).